C1QTNF8 (C1q and TNF related 8)
Description:
May play a role as ligand of RXFP1.
Synonyms: CTRP8; UNQ5829
Tractability: Antibody: UniProt places it where antibodies can reach, with high confidence; UniProt predicts a signal peptide or a membrane-spanning region; its Gene Ontology location is reachable by antibodies, with medium confidence.
Gene: Protein-coding gene on chromosome 16 (1,088,226 to 1,099,401, reverse strand). Ensembl gene ENSG00000184471.
Subcellular location: Secreted
Gene Ontology:
Molecular function: protein binding
Biological process: positive regulation of cell motility
Cellular component: extracellular region
Genetic constraint (gnomAD): Loss-of-function variants: 27 observed, 17.42 expected, observed/expected ratio (o/e) 1.55, 90% interval 1.13 to 1.92. The synonymous counts are far from expectation, so gnomAD's model fits this gene poorly and the ratio says little. Missense variants: 484 observed, 312.81 expected, observed/expected ratio (o/e) 1.55, 90% interval 1.44 to 1.67. Synonymous variants: 208 observed, 143.77 expected, observed/expected ratio (o/e) 1.45, 90% interval 1.29 to 1.62.
Homologues: Orthologues: chimpanzee C1QTNF8 (98% identical), macaque C1QTNF8 (93% identical), pig C1QTNF8 (83% identical), tropical clawed frog c1qtnf1 (50% identical). Paralogues in human: C1QTNF1 (48% identical), C1QTNF6 (48% identical), COL8A2 (26% identical), OTOL1 (26% identical), C1QTNF3 (26% identical), COL10A1 (26% identical), C1QTNF4 (25% identical), C1QTNF5 (25% identical), C1QTNF9 (25% identical), COL8A1 (25% identical), C1QL2 (25% identical), C1QTNF9B (25% identical), and 11 more.
Diseases named in the same sentence as C1QTNF8 in open-access papers:
C1QTNF8 is named in the same sentence as 12 diseases in open-access papers, as found by Europe PMC text mining. Sharing a sentence is not in itself a finding about the gene and the disease. The quoted sentences say what the papers report.
glioblastoma (8 papers, 2015 to 2023). The most malignant astrocytic tumor (WHO grade IV). "For example, the expression level of the EXT2 gene is increased in glioblastoma; C1QTNF8 promotes temozolomide resistance; CACNA1H promotes GBM cell proliferation and migration." (PMID 34827152, 2021).
C1QTNF8 also shares sentences with these, for which no sentence is quoted: cancer (2 papers); tumor (2); brain cancer (1); brain tumor (1); colon cancer (1); glioma (1); liver cancer (1); lung carcinoma (1); osteoarthritis (1); osteosarcoma (1); thyroid cancer (1).